MIR30C1 (microRNA 30c-1)
Synonyms: hsa-mir-30c-1; MIRN30C1; mir-30c-1
Gene: MicroRNA gene on chromosome 1 (40,757,284 to 40,757,372, forward strand). Ensembl gene ENSG00000207962.
Gene Ontology:
Biological process: miRNA-mediated post-transcriptional gene silencing
Cellular component: RISC complex
Homologues: Orthologues: chimpanzee ptr-mir-30c-1 (100% identical), macaque mml-mir-30c-1 (100% identical), mouse Mir30c-1 (99% identical), rabbit MIR30C1 (98% identical), guinea pig MIR30C1 (96% identical), dog MIR30C1 (91% identical), pig ssc-mir-30c-1 (87% identical), tropical clawed frog xtr-mir-30c-1 (85% identical). Paralogues in human: MIR30B (65% identical), MIR30C2 (63% identical), MIR30D (36% identical), MIR30E (35% identical), MIR30A (28% identical).
Diseases named in the same sentence as MIR30C1 in open-access papers:
MIR30C1 is named in the same sentence as 3 diseases in open-access papers, as found by Europe PMC text mining. Sharing a sentence is not in itself a finding about the gene and the disease. The quoted sentences say what the papers report.
melanoma (1 paper, 2024). A malignant, usually aggressive tumor composed of atypical, neoplastic melanocytes. "MicroRNA 30c-1 (MIR30C1) is known to inhibit the progression of prostate cancer and the invasion of melanoma." (PMID 38678251, 2024).
MIR30C1 also shares sentences with these, for which no sentence is quoted: breast carcinoma (2 papers); prostate carcinoma (1).